ITGAM (integrin subunit alpha M)
Diseases named in the same sentence as ITGAM in open-access papers (continued):
Sharing a sentence is not in itself a finding about the gene and the disease.
lung adenocarcinoma (5 papers, 2018 to 2025). A carcinoma that arises from the lung and is characterized by the presence of malignant glandular epithelial cells. "In this study, the expression of serum exosomal ITGAM in the advanced lung adenocarcinoma group was significantly higher than that in the healthy control group." (PMID 35291954, 2022). "The IHC staining of lung adenocarcinoma tissues and nearby tissues was used to detect the expression of ITGAM and CLU." (PMID 35291954, 2022). "Besides, ITGAM expression in lung adenocarcinoma tissues was higher than that in adjacent tissues." (PMID 35291954, 2022). "In conclusion, ITGAM and CLU were identified as serum exosomal protein markers of lung adenocarcinoma." (PMID 35291954, 2022). "We used WB to validate the differential expression of serum exosomal ITGAM and CLU among the advanced lung adenocarcinoma group, early lung adenocarcinoma group, and healthy control group." (PMID 35291954, 2022). "We considered serum exosomal proteins ITGAM and CLU as markers for lung adenocarcinoma." (PMID 35291954, 2022). "ITGAM and CLU were identified as serum exosomal protein markers of lung adenocarcinoma." (PMID 35291954, 2022).
staphylococcus aureus infection (5 papers, 2018 to 2025). An infectious process in which the bacteria Staphylococcus aureus is present. "KEGG enrichment identified neutrophil-mediated defense mechanisms as central shared pathways, with Staphylococcus aureus infection (C1QA/B/C, P = 2.2×10-11) and neutrophil extracellular trap formation (ITGAM/ITGB2, P = 7.3×10-10) exhibiting strongest associations." (PMID 41199823, 2025). "Among which, we also performed the PPI network of several DEGS including C3, HLA-DRB5, ICAM1 and HLA-DRB1, ITGAM, and CFD that involved in the staphylococcus aureus infection signaling pathway." (PMID 30186855, 2018).
abdominal aortic aneurysm (4 papers, 2021 to 2024). Enlargement and ballooning of the vessel that supplies arterial blood to the abdomen, pelvis and legs. "In addition, high expression of ITGAM is associated with unstable atherosclerotic plaques, and ITGAM knockout reduces macrophage infiltration, MMP9 expression, and elastin and collagen degradation in mouse abdominal aortic aneurysm models." (PMID 35656397, 2022). "Integrin subunit alpha M (ITGAM) gene encodes Integrin αM (CD11b), which might promote the development and progression of abdominal aortic aneurysm via mediating the adhesion of endothelial cells and the transendothelial migration of circulating monocytes/macrophages." (PMID 34957234, 2021).
diabetic nephropathy (4 papers, 2021 to 2024). "Hub genes (FPR3, C3AR1, CD14, ITGB2, RAC2 and ITGAM) related to iron death in diabetic nephropathy were obtained through gene expression differential analysis between different subtypes." (PMID 34735495, 2021). "In diabetic nephropathy, ITGAM may contribute to kidney injury by increasing macrophage recruitment in the kidneys and causing histological abnormalities in the glomeruli." (PMID 37760894, 2023). "Finally six Hub genes related to iron death in diabetic nephropathy were obtained, including FPR3, C3AR1, CD14, ITGB2, RAC2 and ITGAM." (PMID 34735495, 2021).
lung disease (4 papers, 2013 to 2023). "In our study, this pathway was significantly extracted from general SSc (upregulated proteins) and lung disease related to SSc (downregulated proteins) subgroups (ITGB1;ACTN1;ICAM1;ITGAM;MMP9)." (PMID 36732374, 2023). "Our results show that ITGAM and MMP9 proteins are mainly dysregulated for leukocyte transendothelial migration, indicating that they might promote lung disease related to SSc by affecting this procedure." (PMID 36732374, 2023).
Neonatal sepsis (4 papers, 2020 to 2025). Systemic inflammatory response to infection in newborn babies. "ITGAM (CD11b) was reported as an early diagnostic marker of neonatal sepsis." (PMID 32908583, 2020).
systemic sclerosis (4 papers, 2012 to 2023). A chronic disorder, possibly autoimmune, marked by excessive production of collagen which results in hardening and thickening of body tissues. "GWAS have strongly implicated the SNP rs1143679 in the ITGAM gene, which results in an arginine to histidine change at position 77 in the extracellular domain of CD11b, with the risk of SLE, systemic sclerosis, and certain cancers." (PMID 31673770, 2019). "The relationship between ITGAM and systemic sclerosis has also been reported." (PMID 37465687, 2023). "For instance, ITGAM and its variant (rs1143679, Arg77His) are associated with SLE and systemic sclerosis (SSc)." (PMID 22577522, 2012).
colonic adenomas (3 papers, 2020 to 2024). "ITGAM was expressed the highest in HC, followed by colonic adenomas, and the lowest in primary CRC and CRC with hepatic metastases." (PMID 37040507, 2023). "Subsequently, we examined the ITGAM expression in plasma exosomes from HC, colonic adenomas, primary CRC, and CRC with hepatic metastases." (PMID 37040507, 2023).
malignant glioma (3 papers, 2016 to 2020). A grade III or grade IV glioma arising from the central nervous system. "For instance, ITGAM was reported to play a critical role in invasive growth and angiogenesis in malignant gliomas." (PMID 32211315, 2020).
monocytic leukemia (3 papers, 2017 to 2025). "Upregulation of ITGAM and CD86 following LSD1 inhibition was correlated with myeloid differentiation, inhibition of human monocytic leukemia cell proliferation, and sensitization of AML cells to all-trans-retinoic acid." (PMID 31740623, 2019).
Shock (3 papers, 2012 to 2022). The state in which profound and widespread reduction of effective tissue perfusion leads first to reversible, and then if prolonged, to irreversible cellular injury. "It is also associated with FOSL2 in pediatric septic shock and LILRB2 and ITGAM in pediatric resolved SIRS." (PMID 32318053, 2020).
Sleep apnea (3 papers, 2015 to 2020). An intermittent cessation of airflow at the mouth and nose during sleep is known as sleep apnea. "Interestingly, neither ITGAM nor ANXA3 were altered in either sleep apnea or “sleepy” subjects suggesting that they may be better suited for detecting acute sleep loss than for identifying patients with chronic sleep disruption." (PMID 25873764, 2015).
Gliosis (2 papers, 2021 to 2022). Gliosis is the focal proliferation of glial cells in the central nervous system. "Gliosis and retinal microglial activation were measured by using GFAP, CD68, and ITGAM mRNA quantification and GFAP, CD68, and Iba1 immunofluorescence stainings." (PMID 35236378, 2022).
liver cirrhosis (2 papers, 2018 to 2022). "Elevated ITGAM levels have been observed in peripheral blood leukocytes of individuals with liver cirrhosis." (PMID 36358697, 2022).
lung squamous cell carcinoma (2 papers, 2018 to 2024). "In addition, higher expression of CD163, CD206 (MRC1), and CD11b (ITGAM) in patients with lung squamous cell carcinoma was associated with lower overall survival." (PMID 38521953, 2024).
nutritional disorder (2 papers, 2020 to 2021). Any condition related to a disturbance between proper intake and utilization of nourishment. "The study aimed to assess the relationship between a single nucleotide polymorphism (SNP) -323G > A of the ITGAM and the occurrence of nutritional disorders in patients with CHF." (PMID 34635743, 2021). "Determination of the -323G > A SNP in the ITGAM may prove to be a useful marker (after confirmation in further studies and appropriate validation) in the assessment of the risk of nutritional disorders in patients with CHF." (PMID 34635743, 2021). "In that aspect AA genotype of ITGAM gene may be a useful marker assessing the risk of nutritional disorders in patients with CHF." (PMID 34635743, 2021). "Determination of the ITGAM SNP (-323G>A) may be a useful marker in the assessment of the risk of nutritional disorders in patients with HNC undergoing RT." (PMID 33327591, 2020). "Despite these limitations, to our knowledge, this is the first study to show that the assessment of ITGAM SNP (-323G>A) may be a useful marker in assessing the risk of nutritional disorders in patients with HNC undergoing RT." (PMID 33327591, 2020). "In this study, we have aimed at the assessment of the relationship between ITGAM gene regulatory region (−323G > A) SNPs and the incidence of nutritional disorders in cachectic patients with CHF." (PMID 34635743, 2021). "It should be noted that the available literature lacks studies related to the relationship between ITGAM gene status and nutritional disorders." (PMID 33327591, 2020). "The aim of this study was to assess the relationship between SNPs located in the regulatory region of the ITGAM gene (-323G>A) and the occurrence of nutritional disorders in patients with HNC undergoing IMRT." (PMID 33327591, 2020). "However, assessment of genetic markers, such as ITGAM (-323G > A) can serve (after appropriate validation) as a putative promising marker for nutritional disorders screening in CHF patients, because of its correlation with patients’ clinical and nutritional features." (PMID 34635743, 2021). "We would like to point out that there are no studies directly related to the relationship between ITGAM gene status and nutritional disorders in the available literature." (PMID 34635743, 2021). "However, as far as we know, no studies have been performed regarding the correlation between the occurrence of nutritional disorders in patients with CHF and the ITGAM gene status." (PMID 34635743, 2021). "However, to our knowledge, there are no studies on the correlation between the ITGAM gene status and the development of nutritional disorders in patients with HNC." (PMID 33327591, 2020).
aortic aneurysm (1 paper, 2022). A ruptured aneurysm located in the wall of the proximal portion of the descending aorta proceeding from the arch of the aorta. "ITGAM acts as an adhesion molecule and mediated the migration of circulating monocytes/macrophages; thus, ITGAM deficiency could ameliorate aortic aneurysm expansion." (PMID 35837612, 2022).
coronary atherosclerosis (1 paper, 2023). Atherosclerosis of the coronary vasculature. "Finally, ITGAM has been identified as an inducer of coronary atherosclerosis through endothelial cell dysfunction." (PMID 37623250, 2023).
discoid lupus erythematosus (1 paper, 2020). A chronic, autoimmune skin condition that manifests with a red, scaling rash, most often found on the face, ears, and scalp; these lesions often lead to permanent scarring and dyspigmentation. "Study in the Finnish and Swedish SLE patients found the correlation of ITGAM with cutaneous discoid lupus erythematosus (DLE) and LN as well as Ro/SSA auto-antibody positive." (PMID 32771030, 2020).
Hernia (1 paper, 2021). "Therefore, these STX4 and ITGAM genes might be involved in several processes related to hernia development, such as cell adhesion and also inflammation." (PMID 34773987, 2021).
hyperuricemia (1 paper, 2024). An abnormally high level of uric acid. "Here, integrin ITGAM is reported as the hub gene promoting macrophage M2 polarization in hyperuricemia‐related CKD." (PMID 38911067, 2024). "Through the integration and analysis of transcriptomic and phosphoproteomic data from renal tissue stimulated by hyperuricemia, we identified ITGAM as a central node." (PMID 38911067, 2024). "Our findings shed light on the molecular mechanism underlying kidney fibrosis in hyperuricemia‐related CKD, highlighting the significance of ITGAM expression, and signaling as potential therapeutic targets for the prevention and delay of CKD progression." (PMID 38911067, 2024). "Here, we aim to investigate whether and how macrophage integrin αM (ITGAM) contributes to hyperuricemia‐related CKD." (PMID 38911067, 2024). "Highly colocated p‐FAK and ITGAM indicated the hypothesis that activation of FAK signaling might be related to ITGAM and they coworked together mediating macrophage polarization in hyperuricemia‐related CKD." (PMID 38911067, 2024). "Furthermore, upregulation of ITGAM was confirmed by human renal biopsy section in CKD patients with primary hyperuricemia." (PMID 38911067, 2024). "In summary, macrophage integrin ITGAM might play the vital role in mediating kidney fibrosis of hyperuricemia‐related CKD through activating its downstream focal adhesion pathway and promoting macrophage M2 polarization." (PMID 38911067, 2024). "We examined the expression of frequently reported main ligands and found a significant upregulation of ICAM‐1 and fibronectin, which indicated potential role of ITGAM in cell–ECM and cell–cell interactions in kidneys of hyperuricemia‐related CKD." (PMID 38911067, 2024).
Infertility (1 paper, 2020). "The results revealed that ITGAM protein was downregulated in seminoma, and may be involved in spermatogenesis, motility function, and infertility." (PMID 33104706, 2020).
kidney transplant (1 paper, 2022). A surgical procedure in which one or both kidneys from a donor are implanted into a recipient. "In this study, CCR5, CD86, CD8A, ITGAM, and PTPRC were up-regulated and had the positive correlation with allograft rejection in kidney transplant patients." (PMID 36330810, 2022). "Five diagnostic genes were further identified, including CCR5, CD86, CD8A, ITGAM, and PTPRC, which were positively correlated with allograft rejection after the kidney transplant." (PMID 36330810, 2022). "Thus, it can be seen that PTPRC, CD86, CCR5, and ITGAM could be considered as potential targets of PREDNISONE, EPOETIN BETA, ABATACEPT, MARAVIROC, and CLARITHROMYCIN, which may provide novel treatment options for kidney transplant patients with allograft rejection." (PMID 36330810, 2022).
rosacea (1 paper, 2021). A chronic erythematous skin disorder that affects the face. "The results of RT-qPCR showed that carvedilol alleviated the elevated inflammatory cytokines (TNF-α, IL-6, and IL-8) and macrophage chemotactic factors (ITGAM, ITGB2) of rosacea-like skin, indicating that inflammation and macrophages are inhibited." (PMID 34322115, 2021). "Besides, macrophages in rosacea were supported by significant upregulation of cell markers of macrophages and upregulation of ITGB2 and ITGAM mRNA expression as well." (PMID 34322115, 2021).
seminoma (1 paper, 2020). A radiosensitive malignant germ cell tumor found in the testis (especially undescended), and extragonadal sites (anterior mediastinum and pineal gland). "Three novel biomarkers, TYROBP, CD68 and ITGAM, were identified from databases and correlated with poor prognosis in patients with seminoma." (PMID 33104706, 2020). "The univariate Cox proportional hazards regression analyses showed that CD68 and ITGAM were positively correlated with overall survival in seminoma." (PMID 33104706, 2020). "However, direct evidence on ITGAM and its molecular mechanism in seminoma are limited in the present literature." (PMID 33104706, 2020). "The protein level of ITGAM was higher in seminoma tissues than in normal tissues." (PMID 33104706, 2020). "In conclusion, our study demonstrated that TYROBP, CD68, and ITGAM could be regarded as prognostic biomarkers and therapeutic targets for seminoma patients." (PMID 33104706, 2020). "Ultimately, TYROBP, CD68, and ITGAM were considered three prognostic biomarkers in seminoma." (PMID 33104706, 2020).
Umbilical hernia (1 paper, 2021). Protrusion of abdominal contents through a defect in the abdominal wall musculature around the umbilicus. "Moreover, a SNP with predicted deleterious function was identified in the ITGAM gene, which might be related to the appearance of umbilical hernia in pigs." (PMID 33513662, 2021).
tumor (2,544 papers, 1996 to 2026). "The literature reports that TYROBP, TLR4, and ITGAM are involved in the BP to activate macrophages that have been reported as tumor-associated and as the main component of the immune environment in OS35–37." (PMID 34588497, 2021). "One meeting report in 2016 described that ITGAM protein positive tumor associated macrophages were associated with tumor angiogenesis promotion and immunosuppression." (PMID 33104706, 2020). "Of note, the last study by Verhaak’s group highlighted that Mesenchymal GB are enriched in tumor associated microglial cells, as the macrophage marker ITGAM (CD11b) appeared, among others, to be specifically overexpressed in this subtype." (PMID 29156849, 2017). "In this study, we firstly revealed that the level of some proteins (such as NRP2, TIMP1, ITGB2, ITGAM) associated with tumor metastasis promotion was decreased in the exosomes derived from MNDA knockdown M2 macrophages, which could be taken up by HCC cells." (PMID 38904028, 2024). "Studies have reported that ITGAM is significantly associated with tumor metastasis." (PMID 34588497, 2021). "In the relma-cel study, the expression levels of tumor-associated fibroblast markers (AP, TNC, CSPG4, PDGFRA, S100A4, ASPN, STC1, and ITGAM) were higher in the patients with PR than with CR." (PMID 39858099, 2025). "Eosinophils bind ICAM-1 in the surface of tumor cells through leukocyte function-associated antigen 1 (LFA-1) (CD11a/CD18 integrin) and ITGAM (CD11b/CD18 integrin)." (PMID 38892286, 2024). "We provide compelling evidence that cancer cell-derived ITGA6-ITGB3-positive exosomes facilitate tumor proliferation and metastasis; however, macrophage-derived ITGAM-positive exosomes inhibit CRC development and metastasis." (PMID 37040507, 2023). "At the same time, the spatial distribution of the ITGAM + ITGB2-ICAM1 signaling axis was also concentrated in the area of close contact between tumor cells and T cells, which further reflects the intense immune struggle in this area." (PMID 37120690, 2023). "Although the expression levels of myeloid marker gene (ITGAM) in all the tumor types were relatively lower in the CB method, the enrichment scores of the mark pathway were even higher when comparing with those of the PEMG method." (PMID 38094301, 2023). "Numerous studies have indicated that myeloid-derived suppressor cells (MDSCs) with high expression of ITGAM are important in promoting tumor progression." (PMID 35291954, 2022). "ITGAM was higher expressed in tumor tissues compared with normal tissues, while CLU was higher expressed in normal tissues." (PMID 35291954, 2022). "The expression of ITGB2 and ITGAM in the dataset GSE9476 was also higher in tumor samples compared with donors." (PMID 35501867, 2022). "OLFML2B was highly co-expressed with tumor-associated macrophage markers such as CD14, CD163, CSF1R, ITGAM, and MRC1." (PMID 34868901, 2021). "Highly relevant nodes in the modules, including STAT3, SLC11A1, and ITGAM, have been reported to promote tumor proliferation, angiogenesis, migration, and invasiveness." (PMID 32211315, 2020). "Consistently, RNAseq analysis of human cancers revealed a strong positive correlation between the expression of Treg markers (FOXP3, IL2RA) and myeloid cell markers (MRC1, CD14, and ITGAM) across several tumor types." (PMID 32782249, 2020). "More recently, ITGAM has also been defined as a marker for myeloid suppressor cells, which has been reported to be used by malignant cells to suppress anti-tumor immunity and promote malignant expansion or refractory therapy." (PMID 32039005, 2019). "ITGAM is considered a marker for myeloid-derived suppressor cells responsible for tumor escape from host immunity and treatment refractoriness." (PMID 31740623, 2019).